ATG13 (autophagy related 13)
Diseases named in the same sentence as ATG13 in open-access papers (continued):
Sharing a sentence is not in itself a finding about the gene and the disease.
pulmonary fibrosis (1 paper, 2025). Chronic progressive interstitial lung disorder characterized by the replacement of the lung tissue by connective tissue, leading to progressive dyspnea, respiratory failure, or right heart failure. "In a PM2.5-induced pulmonary fibrosis model, PM2.5 was shown to downregulate ALKBH5 expression, promote m6A modifications at specific sites of Atg13 mRNA, and activate ULK complex (composed of ULK1, Atg13, FIP200, and Atg101)-mediated autophagy." (PMID 40391214, 2025).
reovirus infection (1 paper, 2017). "To examine the importance of the autophagy machinery for reovirus infection, we used SV40 transformed MEF cell lines with a knock-out for a specific autophagy-related gene: Atg3, Atg5, or Atg13." (PMID 28934149, 2017).
sarcoma (1 paper, 2019). A usually aggressive malignant neoplasm of the soft tissue or bone. "Exposure of sarcoma cells to neratinib, [pazopanib + entinostat], or the three-drug combination enhanced YAP and TAZ phosphorylation in parallel to a profound inactivation of mTOR resulting in phosphorylation of gate-keeper protein ATG13 S318." (PMID 31380285, 2019).
sarcopenia (1 paper, 2021). Progressive decline in muscle mass due to aging which results in decreased functional capacity of muscles. "During the course of sarcopenia progression in SAMP8 mice, elevated Atg13 and LC3-II levels were associated with the accumulation of p62 and lysosome-associated membrane protein 1 (LAMP1), suggesting that poor fusion between autophagosomes and lysosomes and impaired mitophagy in sarcopenic mice." (PMID 34881083, 2021).
schizophrenia (1 paper, 2025). A major psychotic disorder characterized by abnormalities in the perception or expression of reality. "We identified 22 novel isoforms for the schizophrenia risk gene autophagy-related protein 13 (ATG13)." (PMID 40988056, 2025).
staphylococcus aureus infection (1 paper, 2015). An infectious process in which the bacteria Staphylococcus aureus is present. "Silencing of ATG13 transcripts in T. molitor larvae showed a reduced survivability of 39 and 38% in response to Escherichia coli and Staphylococcus aureus infection." (PMID 26136688, 2015).
vitiligo (1 paper, 2021). Generalized well circumscribed patches of leukoderma that are generally distributed over symmetric body locations and is due to autoimmune destruction of melanocytes. "Therefore, we obtained the circRNA-ceRNA networks that might have the important roles in vitiligo pathology: hsa_circ_0007716 – hsa-miR-149-5p – ATG13/SEMA4D, hsa_circ_0003770 –hsa-miR-320a-3p – SMAD3 and hsa_circ_0087961 – hsa-miR-27a-3p - PAXILLIN." (PMID 33968138, 2021). "As the results shown that the expression of ANKRD6, ATG13, SEMA4D, SMAD3, and PAXILLIN were all significantly downregulated in vitiligo." (PMID 33968138, 2021). "Furthermore, we detected the expression of target genes such ANKRD6, ATG13, SEMA4D, SMAD3, and PAXILLIN to verify that these circRNA-ceRNA networks are involved in the pathological process of vitiligo." (PMID 33968138, 2021).
tumor (17 papers, 2015 to 2026). "In tumor cells, ATG13 knockout impedes cell cycle progression and inhibits proliferation in both in vitro and in vivo models." (PMID 40538852, 2025). "Mechanistically, after overexpression, circPKD2 sponge miR-646 and thus promoting ATG13 expression, triggering autophagy, inducing tumor cell apoptosis, and enhancing chemotherapy sensitivity." (PMID 40538852, 2025). "Over-expression of PD-1 or PD-L1 increased autophagy in tumor cells through autophagy-related protein 13 (ATG13) interactions." (PMID 38155974, 2023). "Our data argued that for robust ATG13 serine 318 phosphorylation and toxic autophagosome formation to occur, and thus lead to tumor cell death, required both the inactivation of mTOR and the activation of AMPK." (PMID 27903966, 2017). "To confirm these findings, we then assessed the presence of ATG13 puncta in tumor fragment spheroids." (PMID 26284517, 2015). "In addition, circ-PKD2 in OSCC functions as a tumor suppressor by promoting the expression of autophagy-related 13 (Atg13) through the adsorption of miR-646, thereby enhancing sensitivity to cisplatin." (PMID 38933443, 2024). "The RasV12; scrib, Atg13 tumours, which had limited growth due to ablation of autophagy, remained small when transplanted into autophagy-deficient hosts but proliferated when transplanted into wild-type hosts, thus demonstrating the importance of autophagy and the microenvironment in tumour growth." (PMID 36899813, 2023). "Immunohistochemical staining with validated anti-ULK1 R170me2s or anti-ULK1 pT180 antibody revealed that ULK1 R170K mutation abolished ULK1 R170me2s, and reduced the phosphorylation of ULK1 T180, Atg13 S355, and Beclin 1 S15 in the tumor samples derived from the mice in normoxia condition." (PMID 35246531, 2022). "Notably, expression of ULK1 R170K mutation attenuated low-oxygen-induced phosphorylation of ULK1 T180, Atg13 S355 and Beclin 1 S15, and accordingly further curbed tumor growth with repressed cell proliferation and increased cell death." (PMID 35246531, 2022). "Copper directly binds Unc-51 Like autophagy activating kinase(ULK) and acts as its regulator to promote phosphorylation and activation of autophagy related 13(ATG13), resulting in the formation of the autophagic complex and ultimately tumor growth." (PMID 36882769, 2023). "Meanwhile, mRNA level of LC 3 was remarkably decreased in the tumor tissue of the BJE-H group, and a declining trend was also observed for ATG13 and ATG5." (PMID 32411003, 2020). "In these mouse models, essential autophagy genes, such as ATG5, ATG7, ATG13 or ULK1, are deleted in genome of tumor cells that arise spontaneously in the context of a normal tumor microenvironment and functional immune system." (PMID 32308763, 2020). "Expression of an activated form of mTOR prevented drug-induced phosphorylation of ATG13 S318, prevented autophagosome formation, and significantly reduced tumor cell killing (data not shown)." (PMID 27379204, 2016). "In tumor fragment spheroids grown from 21 tumors, we also found a subset (n = 11) that was sensitive to GDC-0980, a sensitivity that also correlated with the presence of ATG13 puncta." (PMID 26284517, 2015). "In fact, using tumor fragment spheroids derived from patient tumors, we confirmed our findings from the cell lines, showing that the response to GDC-0980 correlates with the presence of ATG13 puncta." (PMID 26284517, 2015). "In contrast, ULK1 inhibitor SBI-0206965 and/or ATG13-KO alone were not strong enough to inhibit tumor growth as efficiently as DKO, indicating that targeting ULK1 and ATG13 together might be a potential anticancer strategy." (PMID 32516310, 2020).
infection (12 papers, 2013 to 2025). The state of being infected such as from the introduction of a foreign agent such as serum, vaccine, antigenic substance or organism. "In bovine viruses, miR-2904 inhibits MDBK cell autophagy by targeting the 3′-UTR region of autophagy-related gene 13 (ATG13) mRNA during the infection of bovine viral diarrhea virus (BVDV)." (PMID 40842844, 2025). "In our study, the phosphorylation level of Atg13 after 36 h of sporozoite infection was 1.685 times that of the uninfected group and 1.309 times that at 6 h after infection." (PMID 38759153, 2024). "We therefore monitored the localization of the ULK complex subunit ATG13 upon infection using an antibody against the endogenous protein." (PMID 30853402, 2019). "The pattern of splicing of genes IL1B, ACSL1 and ATG13 upon infection with H37Ra or H37Rv followed the trend observed in THP-1 macrophages, showing maximum expression in H37Rv infected cells than others." (PMID 28257432, 2017). "Some of these, like ATG13 and ATXN3, are upregulated in VZV-infected cells, whereas, e.g., ATP2A2 is downregulated upon infection." (PMID 38025266, 2023). "Our study showed that the expression of autophagy-related genes ULK1, ATG13, ATG101, Beclin-1, ATG14, MAP1LC3A, and MAP1LC3B was significantly increased and that SQSTM1 was decreased in the muscle with pathogen infection." (PMID 33574492, 2021). "At the initiation of infection, the pathogen ATGs, including ATG1 (BCIN_07g00720), ATG2 (BCIN_14g01550), and ATG13 (BCIN_13g04910), were up‐regulated." (PMID 32301267, 2020). "Similarly, a decreased DENV infection was observed after silencing of Atg13 or FIP200, suggesting that ULK-1-dependent autophagy supports infection of DCs." (PMID 38863700, 2024). "In macrophages derived from peripheral blood of healthy donors (MDMs), we could confirm infection specific alterations in the expression of IL1B, ACSL1, ATG13 and RAB8B isoforms as noted in THP-1 macrophages." (PMID 28257432, 2017).
cancer (8 papers, 2016 to 2025). A tumor composed of atypical neoplastic, often pleomorphic cells that invade other tissues. "Conversely, direct phosphorylation of UKL1 by mTORC1, as well as the direct and indirect ATG13 (Autophagy-related protein 13), stops the autophagy process, which inhibits the growth of cancer cells." (PMID 39765887, 2024). "In both the control and cancer patients, there were positive correlations (p < 0.0001) between KRAS mutational status and the expression of MAP1LC3B, ATG5, ATG10, ATG13, and ATG14." (PMID 39057088, 2024). "CircHADHA promoted autophagy by regulating ATG13 via miR-361 in both colon epithelial and cancer cells." (PMID 36313671, 2022). "Therefore, circHADHA acts as a sponge to competitively bind miR-361 and regulate ATG13 expression and autophagy in colon epithelial and cancer cells." (PMID 36313671, 2022). "Thus, circHADHA promoted autophagy regulated by miR-361 and ATG13 in colon epithelial and cancer cells." (PMID 36313671, 2022). "CircHADHA increased the expression of ATG13 via miR-361 in both colon epithelial and cancer cells." (PMID 36313671, 2022). "Moreover, double knockout (DKO) of ULK1 and ATG13 could block cell cycle progression and significantly decrease cancer cell proliferation in cell line and mouse models." (PMID 32516310, 2020). "We reconfirmed the correlational analysis data with the expression of MAP1LC3B, ATG5, ATG13, and ATG14 in cancer patients, in KRAS-mut compared to KRAS-WT (p < 0.05)." (PMID 39057088, 2024).
colon polyp (1 paper, 2022). "circHADHA was upregulated in colon polyp patients compared with healthy individuals, which competitively recruited miR-361 to promote autophagy by releasing ATG13." (PMID 36313671, 2022).
immune disorders (1 paper, 2022). "ROC curve analysis showed that the AUC of ATG13 was greater than 80%, which, with increased expression, could provide a sign of immune disorders in DCM." (PMID 35327947, 2022).
ATG13 also shares sentences with these, for which no sentence is quoted: glioma (2 papers); acute myocardial infarction (1); anxiety disorder (1); autism (1); Autoimmunity (1); Azoospermia (1); bladder cancer (1); diabetic kidney disease (1); gastric cancer (1); infarction (1); Insulin resistance (1); laryngeal carcinoma (1); malaise (1); metastatic tumours (1); mononucleosis (1); myocardial ischemia (1); Nephropathy (1); oral cancer (1); oral squamous cell carcinomas (1); pancreatic cancer (1); polyp (1); protein folding disorders (1); rectum adenocarcinoma (1); thalassemia (1); triple-negative breast carcinoma (1); type 2 diabetes (1); viral infection (1).